ZNF841 (zinc finger protein 841)
Description:
May be involved in transcriptional regulation.
Synonyms: LOC284371
Tractability: PROTAC: UniProt records ubiquitination sites on it; ubiquitination databases record sites on it.
Gene: Protein-coding gene on chromosome 19 (52,064,465 to 52,095,765, reverse strand). Ensembl gene ENSG00000197608.
Subcellular location: Nucleus
Gene Ontology:
Molecular function: transcription cis-regulatory region binding; sequence-specific double-stranded DNA binding
Biological process: negative regulation of transcription by RNA polymerase II
Cellular component: nucleus
Genetic constraint (gnomAD): Loss-of-function variants: 10 observed, 10.59 expected, observed/expected ratio (o/e) 0.94, 90% interval 0.58 to 1.58. The upper end of that interval is the gene's LOEUF score, 1.58, which puts it in group 6 of 6, group 1 being the genes least tolerant of losing a copy. Missense variants: 1,065 observed, 1,173.1 expected, observed/expected ratio (o/e) 0.91, 90% interval 0.86 to 0.95. Synonymous variants: 369 observed, 390.68 expected, observed/expected ratio (o/e) 0.94, 90% interval 0.87 to 1.03.
Homologues: Orthologues: chimpanzee ZNF841 (99% identical), macaque ZNF841 (95% identical). Paralogues in human: ZNF836 (76% identical), ZNF546 (38% identical), ZNF616 (37% identical), ZNF267 (35% identical), ZNF528 (35% identical), ZNF28 (33% identical), ZNF534 (33% identical), ZNF658 (32% identical), ZNF540 (32% identical), ZNF585B (32% identical), ZNF33A (32% identical), ZNF41 (32% identical), and 164 more.
Diseases named in the same sentence as ZNF841 in open-access papers:
ZNF841 is named in the same sentence as 2 diseases in open-access papers, as found by Europe PMC text mining. Sharing a sentence is not in itself a finding about the gene and the disease. The quoted sentences say what the papers report.
breast carcinoma (1 paper, 2023). "Variants in BICD2 (six cases), FBN1 (four cases), CSGALNACT1 (one case), and ZNF841 (one case) were observed in at least one UKBiobank breast cancer case, but not in any controls." (PMID 38136396, 2023).
prostate carcinoma (1 paper, 2014). A carcinoma that arises from epithelial cells of the prostate gland. "ZNF841 exhibits NMD sensitivity in the sole experiment that monitored this gene, in mononuclear leukocytes taken from both healthy and prostate cancer patients (GSE24204)." (PMID 24621851, 2014).